LYPD1 (LY6/PLAUR domain containing 1)
Description:
Believed to act as a modulator of nicotinic acetylcholine receptors (nAChRs) activity. In vitro increases receptor desensitization and decreases affinity for ACh of alpha-4:beta-2-containing nAChRs. May play a role in the intracellular trafficking of alpha-4:beta-2 and alpha-7-containing nAChRs and may inhibit their expression at the cell surface. May be involved in the control of anxiety.
Synonyms: PHTS; LYPDC1; MGC29643
Tractability: Antibody: UniProt places it where antibodies can reach, with high confidence; its Gene Ontology location is reachable by antibodies, with high confidence; UniProt predicts a signal peptide or a membrane-spanning region; the Human Protein Atlas places it where antibodies can reach.
Gene: Protein-coding gene on chromosome 2 (132,643,286 to 132,671,579, reverse strand). Ensembl gene ENSG00000150551.
Subcellular location: Cell membrane
Subcellular location (Human Protein Atlas): Nucleoplasm; Vesicles; Plasma membrane
Pathways (Reactome):
Metabolism of proteins: Post-translational modification: synthesis of GPI-anchored proteins
Gene Ontology:
Molecular function: acetylcholine receptor inhibitor activity
Biological process: acetylcholine receptor signaling pathway
Cellular component: extracellular region; plasma membrane; synapse
Genetic constraint (gnomAD): Loss-of-function variants: 14 observed, 15.37 expected, observed/expected ratio (o/e) 0.91, 90% interval 0.6 to 1.42. The upper end of that interval is the gene's LOEUF score, 1.42, which puts it in group 5 of 6, group 1 being the genes least tolerant of losing a copy. Missense variants: 165 observed, 176.18 expected, observed/expected ratio (o/e) 0.94, 90% interval 0.82 to 1.07. Synonymous variants: 85 observed, 72.76 expected, observed/expected ratio (o/e) 1.17, 90% interval 0.98 to 1.4.
Homologues: Orthologues: chimpanzee LYPD1 (99% identical), macaque LYPD1 (99% identical), guinea pig LYPD1 (96% identical), rabbit LYPD1 (95% identical), mouse Lypd1 (94% identical), pig LYPD1 (94% identical), dog LYPD1 (86% identical), rat Lypd1 (86% identical). Paralogues in human: LYPD2 (26% identical), CD59 (21% identical), SLURP1 (18% identical).
Diseases named in the same sentence as LYPD1 in open-access papers:
LYPD1 is named in the same sentence as 28 diseases in open-access papers, as found by Europe PMC text mining. Sharing a sentence is not in itself a finding about the gene and the disease. The quoted sentences say what the papers report.
Anxiety (12 papers, 2013 to 2025). Intense feelings of nervousness, tension, or panic often arise in response to interpersonal stresses. "LYNX2, a nicotinic modulatory protein, is encoded by the Lynx2/Lypd1 gene, expressed in key regions of anxiety and fear circuitry, such as the amygdala and medial prefrontal cortex, in addition to other CNS sites, and sites outside the nervous system." (PMID 40236946, 2025). "To assess the translational potential of the LYNX2 (LYPD1) gene for affective disorders, we investigated LYNX2 and its possible association with anxiety in the human population." (PMID 39763615, 2024). "LYPD1 is expressed at high levels in anxiety associated brain areas and plays an important role in regulating anxiety by binding and modulating neuronal nicotinic receptors." (PMID 27098205, 2016). "Mice null for Lynx2/Lypd1 (Lynx2 KO) show elevated basal anxiety-like behavior in tests such as elevated plus maze, light-dark box and social interaction assays." (PMID 40236946, 2025). "Lystar5 demonstrates high sequence similarity with human three-finger neuromodulator Lynx2 (Lypd1), which is related to anxiety." (PMID 41590700, 2025). "Studies in animal models have uncovered the role of the Lynx2 (Lypd1) gene in anxiety-related behaviors." (PMID 39763615, 2024). "We examined variations in the human LYNX2 (LYPD1) gene and their potential effects on anxiety levels in a cohort of 624 participants." (PMID 39763615, 2024). "Ablation of Lypd1 alters the actions of nicotine on glutamatergic signaling in the prefrontal cortex, resulting in elevated anxiety-like behaviors." (PMID 27098205, 2016). "Among the multiple layers of regulation are protein modulators such as Lynx2/Lypd1, which provides negative nicotinic acetylcholine receptor regulation within anxiety-related circuits, such as the amygdala and medial prefrontal cortex, among other brain regions." (PMID 40236946, 2025).
hepatocellular carcinoma (9 papers, 2020 to 2023). A malignant tumor that arises from hepatocytes. "ALKBH5 is downregulated in hepatocellular carcinoma, and it can inhibit tumor proliferation and invasion capacity, depending on the posttranscriptional inhibition of LYPD1." (PMID 35395767, 2022). "ALKBH5 is known to suppress malignant hepatocellular carcinoma cells by epigenetically inhibiting LYPD1 via m6A modification." (PMID 34491904, 2021). "Notably, a previous report showed that ALKBH5-mediated m6A modification of LY6/PLAUR Domain Containing 1 (LYPD1) is recognized by IGF2BP1 and enhances the stability of LYPD1 mRNA in hepatocellular carcinoma." (PMID 35318440, 2022). "In HCC, the malignancy of hepatocellular carcinoma cells is suppressed by ALKBH5 via m6A-guided suppression of the oncogenic driver LYPD1." (PMID 36609413, 2023).
ovarian carcinoma (6 papers, 2019 to 2024). A malignant neoplasm originating from the surface ovarian epithelium. "Anti-LYPD1/CD3 T-cell-dependent bispecific antibody (TDB) can lead polyclonal T cells to activate and target ovarian cancer cells with LYPD1 expression." (PMID 35391800, 2022). "Evidence has been provided showing that LYPD1 is involved in the pathogenesis of ovarian cancer, and, recently, anti-LYPD1/CD3 bispecific antibodies have been tested for the treatment of this tumor type." (PMID 34281234, 2021). "For LYPD1, it is reported that LY6/PLAUR Domain containing 1 (LYPD1) is a novel therapeutic antibody target for ovarian cancer." (PMID 35391800, 2022). "High expression of GJB2, S100A2, SPOCK2, TGM1or EPS8 indicated a poor OS of patients with ovarian cancer, whereas ovarian cancer patients with higher expression of ADAMDEC1, CHEK1, EGFL6, FAM181A, FOXA2, LYPD1, PART1 or XPR1 possessed better OS." (PMID 31794425, 2019). "PAX8 occupies an intragenic enhancer in the LYPD1 gene locus for LYPD1-expressing ovarian cancer cell lines OVCAR3, KURAMOCHI, and COV318 but not OVCAR4, suggesting that PAX8 might contribute to the transcriptional regulation of LYPD1 expression." (PMID 34290299, 2021).
breast carcinoma (2 papers, 2015 to 2022). "Four percent of patient-derived breast cancer xenografts in the cBioPortal show amplification of LYPD1 and mutation in SLITRK2." (PMID 25926557, 2015). "These genes likely play critical roles in cancer progression because cBioPortal analysis revealed amplification and /or mutations of TMEM47, LYPD1 and SLITRK2 in a variety of cancers including breast cancer." (PMID 25926557, 2015). "We next determined whether the expression of LYPD1, TMEM47 and/or SLITRK2 is enriched in a specific intrinsic subtype of breast cancer." (PMID 25926557, 2015).
melanoma (2 papers, 2017 to 2021). A malignant, usually aggressive tumor composed of atypical, neoplastic melanocytes. "Among the top genes with differentially spliced isoforms between primary melanomas and benign melanocytic nevi were RAB6B, MSR1, LYPD1, and COL11A2." (PMID 34281234, 2021). "Although FGF13 shows no statistical significant discrimination between melanoma primary tumors and metastases, we observed that subsets of melanoma metastases show high expression of either FGF13 or LYPD1." (PMID 28112719, 2017).
bladder cancer (1 paper, 2024). "An increasing number of studies have demonstrated that LYPD1 plays an important role in tumors, and it has not been reported in bladder cancer." (PMID 38332160, 2024).
focal segmental glomerulosclerosis (1 paper, 2020). A renal disorder characterized by sclerotic lesions in the glomeruli. "Interestingly, a similar signature (increased expression of LYPD1, PRSS23 and CHD6) was observed in glomerular tissue from kidney disease patients and observed in focal segmental glomerulosclerosis (FSGS) rats, suggesting reactivation of this developmental program upon injury." (PMID 32466429, 2020).
leukemia (1 paper, 2023). A malignant (clonal) hematologic disorder, involving hematopoietic stem cells and characterized by the presence of primitive or atypical myeloid or lymphoid cells in the bone marrow and the blood. "In addition to fluorescence reporter gene integration, we also designed Cre gene integration in two neuron-specific expressed genes (Calcr, Lypd1) and LoxP integration in one leukemia-related gene (Mllt3)." (PMID 37353834, 2023).
serous ovarian cancer (1 paper, 2021). "Collectively, these data demonstrate that bivalent TCBs directed against LYPD1 have compelling efficacy and safety profiles to support its use as a treatment for high-grade serous ovarian cancers." (PMID 34290299, 2021). "The presented efficacy and safety data of the bivalent low affinity anti-LYPD1 TCB QZC131 directed against the PAX8 lineage-driven target LYPD1 supports its therapeutic potential and merits further evaluation as a treatment for advanced high-grade serous ovarian cancer." (PMID 34290299, 2021).
tumor (12 papers, 2020 to 2025). "Decreased expression of ALKBH5 leads to increased 3′UTR m6A modification of LYPD1 mRNA, which in turn results in the increased expression of LYPD1, which promotes tumor cell growth, migration, invasion and metastasis." (PMID 35784761, 2022). "LYPD1 expression is largely tumor-restricted with expression limited to lineage-specific tissues of origin such as the fallopian tube, anterior pituitary gland and neurons in the prefrontal cortex of the brain, as measured by RNA-ISH." (PMID 34290299, 2021). "To selectively target LYPD1-expressing tumor cells with high expression while sparing cells with low expression, we coupled bivalent low-affinity anti-LYPD1 antigen-binding fragments (Fabs) with the anti-CD3 scFv." (PMID 34290299, 2021). "The in vivo xenograft adoptive transfer (AdT) model demonstrates that both VHP354 and QZC131 can broadly activate and redirect cytotoxic T cells toward tumor cells to induce human T cell-mediated cytotoxicity in vivo in an LYPD1- and dose-dependent manner." (PMID 34290299, 2021). "Based upon the high tumor prevalence and the lineage restricted normal tissue profile, LYPD1 is an attractive target for the T cell-engaging therapeutic modality." (PMID 34290299, 2021). "Herein, we describe the transcriptional regulation of LYPD1 expression by PAX8 in HGSOC tumor cells." (PMID 34290299, 2021). "Using ChIP-seq across a panel of HGSOC cell lines, we demonstrated that LYPD1 is a PAX8 lineage-driven tumor antigen and tractable cell-surface drug target in HGSOC." (PMID 34290299, 2021). "Mechanistically, ALKBH5 acts as a tumor suppressor by inhibiting LY6/PLAUR Domain Containing 1 (LYPD1) via a m6A-dependent manner in HCC cells." (PMID 33790968, 2021). "Albeit LYPD1 was judged as a tumor suppressor in HeLaHF cells, few other investigations offered information about its role in cancer." (PMID 32772918, 2020). "In our study, loss of LYPD1 disrupted the proliferation ability and invasion potential of HCC cells, while LYPD1 expression was elevated in tumor tissues and high level of LYPD1 indicated a poorer prognosis of HCC." (PMID 32772918, 2020). "The analysis of HCC cohort from TCGA and three other cohorts from Gene Expression Omnibus (GEO) datasets demonstrated that LYPD1 was up-regulated in tumorous tissues compared with normal tissues." (PMID 32772918, 2020). "Our study reveals that ALKBH5, characterized as a tumor suppressor, attenuates the expression of LYPD1 via an m6A-dependent manner in HCC cells." (PMID 32772918, 2020). "In line with this assumption, LYPD1 has been reported to be a putative tumor suppressor gene because its overexpression in cancer cell lines reduces cell growth likely via induced apoptosis." (PMID 33473258, 2020). "Antitumor activity of CD3-T-cell-binding bispecific antibodies (TCBs) directed against the PAX8 lineage-driven HGSOC tumor antigen LYPD1 showed that anti-LYPD1 TCBs induce T cell activation and in vivo promote inhibition of tumor growth in LYPD1-expressing HGSOC." (PMID 38001616, 2023). "To investigate the antitumor efficacy of bivalent anti-LYPD1 TCBs in comparison to monovalent anti-LYPD1 TCBs, we used the immunodeficient NOD SCID gamma mouse (NSG) with human PBMCs delivered by adoptive transfer 14 days prior to implantation of the LYPD1-expressing tumor cells." (PMID 34290299, 2021). "Herein, we described the preclinical efficacy and non-human primate toxicology profile of the monovalent high-affinity and bivalent low-affinity anti-LYPD1 TCBs that selectively target tumor cells expressing the PAX8 lineage-driven cell surface antigen LYPD1 in HGSOC." (PMID 34290299, 2021). "Moreover, the up-regulation of LYPD1 was frequently detected in HCC patients who suffered nodal metastasis or belonged to higher tumor grades/stages." (PMID 32772918, 2020).
tumor (continued). "However, the LYPD1-directed bivalent low affinity TCB demonstrated compelling safety profiles in cynomolgus monkeys and showed selective targeting of LYPD1high and LYPD1medium-expressing tumor cells, supporting anti-LYPD1 TCBs for treatment of advanced stage HGSOC." (PMID 34290299, 2021). "While the monovalent high affinity anti-LYPD1 TCB, VHP354 showed tumor regressions down to 0.3 mg/kg, the in vivo potency of the bivalent low affinity anti-LYPD1 TCB, QZC131 showed tumor growth inhibition at 10-fold higher doses of 3 mg/kg." (PMID 34290299, 2021). "Among downregulated genes, some have tumor suppressive activities, e.g., FBLN2, LYPD1, SVEP1." (PMID 41469472, 2025). "We investigated the anti-tumor activity of CD3 T cell engaging bispecific antibodies (TCBs) directed against the PAX8 lineage-driven HGSOC tumor antigen LYPD1 and demonstrated that anti-LYPD1 TCBs induce T cell activation and promote in vivo tumor growth inhibition in LYPD1-expressing HGSOC." (PMID 34290299, 2021).
cancer (5 papers, 2015 to 2025). A tumor composed of atypical neoplastic, often pleomorphic cells that invade other tissues. "Here we have systematically illustrate the cancer-related behavior of LYPD1 and its upstream partners within the m6A-based modulation, providing novel insights into functions of LYPD1 in tumorigenesis." (PMID 32772918, 2020). "And pan-cancer analysis manifested that expression of LYPD1 was widely elevated across numerous cancers." (PMID 32772918, 2020).
infection (1 paper, 2025). The state of being infected such as from the introduction of a foreign agent such as serum, vaccine, antigenic substance or organism. "By contrast, infection induced only a slightly increased expression of Ly6/Plaur domain containing 1 (Lypd1) in the KO mice lacking functional Ilc2." (PMID 40559579, 2025).
LYPD1 also shares sentences with these, for which no sentence is quoted: anxiety disorder (1 paper); benign ovarian tumors (1); bipolar disorder (1); colon cancer (1); gastric cancer (1); glomerular disease (1); lung carcinoma (1); neurodegenerative disease (1); nicotine dependence (1); non-small cell lung carcinoma (1); panic disorder (1); schizophrenia (1); skin abnormalities (1); triple-negative breast carcinoma (1); ulcers (1); vasculopathy (1).